GPSM2 (G protein signaling modulator 2)
Description:
Plays an important role in mitotic spindle pole organization via its interaction with NUMA1. Required for cortical dynein-dynactin complex recruitment during metaphase. Plays a role in metaphase spindle orientation. Also plays an important role in asymmetric cell divisions. Has guanine nucleotide dissociation inhibitor (GDI) activity towards G(i) alpha proteins, such as GNAI1 and GNAI3, and thereby regulates their activity (By similarity).
Synonyms: LGN; Pins; CMCS; DFNB82
Tractability: Antibody: UniProt places it where antibodies can reach, with high confidence; its Gene Ontology location is reachable by antibodies, with medium confidence. PROTAC: ubiquitination databases record sites on it.
Gene: Protein-coding gene on chromosome 1 (108,875,350 to 108,934,545, forward strand). Ensembl gene ENSG00000121957.
Subcellular location: Cytoplasm; Cytoplasm, cell cortex; Cytoplasm, cytoskeleton, spindle pole; Lateral cell membrane
Subcellular location (Human Protein Atlas): Cytosol; Centrosome
Pathways (Reactome):
Signal Transduction: G alpha (i) signalling events
Gene Ontology:
Molecular function: dynein complex binding; identical protein binding; protein binding; protein domain specific binding; G-protein alpha-subunit binding; GDP-dissociation inhibitor activity; GTPase regulator activity
Biological process: establishment of mitotic spindle orientation; maintenance of centrosome location; mitotic spindle organization; positive regulation of protein localization to cell cortex; positive regulation of spindle assembly; regulation of mitotic spindle organization; asymmetric cell division; G protein-coupled receptor signaling pathway
Cellular component: cell cortex; cell cortex region; cytoplasm; cytosol; lateral cell cortex; lateral plasma membrane; mitotic spindle pole; protein-containing complex; raps-insc complex; spindle pole
Genetic constraint (gnomAD): Loss-of-function variants: 22 observed, 36.54 expected, observed/expected ratio (o/e) 0.6, 90% interval 0.43 to 0.86. The synonymous counts are far from expectation, so gnomAD's model fits this gene poorly and the ratio says little. Missense variants: 398 observed, 495.84 expected, observed/expected ratio (o/e) 0.8, 90% interval 0.74 to 0.87. Synonymous variants: 143 observed, 186.05 expected, observed/expected ratio (o/e) 0.77, 90% interval 0.67 to 0.88.
Gene-disease validity (ClinGen):
ClinGen rates the evidence that GPSM2 causes each of these diseases.
Chudley-McCullough syndrome (autosomal recessive): Definitive.
Homologues: Orthologues: chimpanzee GPSM2 (99% identical), macaque GPSM2 (99% identical), pig GPSM2 (94% identical), rabbit GPSM2 (94% identical), mouse Gpsm2 (91% identical), dog GPSM2 (91% identical), rat Gpsm2 (89% identical), zebrafish gpsm2 (66% identical). Paralogues in human: GPSM1 (56% identical), TTC28 (33% identical), TTC24 (16% identical), RAPSN (13% identical), TTC29 (11% identical), GPSM3 (8% identical).
Diseases named in the same sentence as GPSM2 in open-access papers:
GPSM2 is named in the same sentence as 42 diseases in open-access papers, as found by Europe PMC text mining. Sharing a sentence is not in itself a finding about the gene and the disease. The quoted sentences say what the papers report.
breast carcinoma (10 papers, 2013 to 2026). "Other research has highlighted GPSM2’s association with drug resistance in breast cancer and its potential as a therapeutic target to enhance drug sensitivity, particularly concerning chemotherapy drugs such as paclitaxel." (PMID 38674408, 2024). "Their expression levels were also associated with advanced tumor stages, and GPSM2 was found to be related to worse distant metastasis-free survival in patients with breast cancer." (PMID 34572330, 2021). "Thus, it needs further comprehensive and in-depth prospective study with enough samples to demonstrate that nucleus expression of GPSM2 is associated with high rate of recurrence in breast cancer patients." (PMID 32195179, 2020). "Correlations between GPSM2 and the clinical features of breast cancer patients have been documented." (PMID 38674408, 2024). "Research has demonstrated that LGN/GPSM2 is significantly upregulated in breast cancer cells, playing a crucial role in cytokinesis." (PMID 38674408, 2024). "GPSM2 has a role in breast cancer cell division and promotes tumor proliferation and metastasis in hepatic cellular cancer." (PMID 36134028, 2022). "Previous studies have reported the role of GPSM1 and GPSM2 in several cancers, including hepatocellular carcinoma, pancreatic cancer, and breast cancer." (PMID 34827528, 2021). "To summarize, in the GPSM family genes, GPSM2 expression was consistently higher in people with breast cancer than in normal controls at both mRNA and protein levels." (PMID 34572330, 2021). "In particular, GPSM2 co-expressed genes play essential roles in the cell cycle and DNA damage pathways in breast cancer growth." (PMID 34572330, 2021). "In particular, GPSM2 is widely known to modulate mitotic spindle orientation, and its significance in breast cancer has been reported by earlier studies." (PMID 34572330, 2021). "Consistent with previous research, we also found that the expression level of GPSM2 in breast cancer tissues increased significantly when compared to normal samples from Oncomine and UALCAN analysis." (PMID 34572330, 2021). "Prior studies have confirmed the contributions of each gene individually in various types of cancer, with GPSM2 so far being the most relevant to breast cancer." (PMID 34572330, 2021). "Survival analysis then showed breast cancer patients with high GPSM2 expression to have consistently worse distant metastasis-free survival." (PMID 34572330, 2021). "Taken together, we propose that GPSM2 is a potential prognostic marker and therapeutic target for breast cancer." (PMID 34572330, 2021). "Correlation between GPSM2 expression and clinical characteristics in breast cancer patients (n = 219)." (PMID 32195179, 2020). "Correlation between GPSM2 subcellular localization and clinical characteristics in breast cancer patients (n = 91)." (PMID 32195179, 2020). "Taken together, we report here the clinical value of GPSM2, especially GPSM2 nuclear expression, in breast cancer." (PMID 32195179, 2020). "In conclusion, our results strongly suggested that GPSM2 was an independent prognostic factor in breast cancer." (PMID 32195179, 2020). "To investigate the clinical value of GPSM2 in invasive breast cancer, we performed IHC analysis of 189 breast cancer tissue samples with available long-term follow-up medical records." (PMID 32195179, 2020). "PBK has been identified as a kinase regulating mitosis by phosphorylation of GPSM2 (G-protein signaling modulator 2) in breast cancer cells." (PMID 25745361, 2015). "LGN/GPSM2 plays a key role in cell division in breast cancer." (PMID 41362722, 2026). "Furthermore, GPSM2 appears to negatively affect the efficacy of paclitaxel, a commonly used and well-tolerated chemotherapeutic agent for breast cancer." (PMID 38674408, 2024). "Furthermore, analysis revealed that GPSM1 had weak protein expression, in contrast to the moderate expression of GPSM2 in clinical breast cancer specimens." (PMID 34572330, 2021).
breast carcinoma (continued). "Univariate Cox analysis revealed that advanced age, TNM stage III/IV, and metastasis, but not GPSM2 expression, were independent high-risk factors for breast cancer survival." (PMID 34572330, 2021). "In addition, previous studies have reported the role of GPSM2 in several cancers, including hepatocellular carcinoma, pancreatic cancer, and breast cancer." (PMID 34827528, 2021). "Furthermore, bioinformatics analysis and in vivo verification have suggested that GPSM2 negatively influenced patient response to paclitaxel, one of the most effective and well-tolerated chemotherapy drugs for breast cancer." (PMID 34572330, 2021). "In this study, we identified GPSM2 as an indicator of poor prognosis in breast cancer." (PMID 32195179, 2020). "We examined the subcellular localization of GPSM2 in breast cancer tissues." (PMID 32195179, 2020). "In addition, one study suggested GPSM2 was involved in the cell division of breast cancer cells and was regulated by PBK/TOPK." (PMID 32195179, 2020). "In addition, one study has observed aberrant expression of GPSM2 in breast cancer, but, its clinical value needs to be further explored." (PMID 32195179, 2020). "GPSM2 plays the role of an oncogene in liver cancer, breast cancer, and pancreatic cancer." (PMID 33169793, 2020). "To summarize, our study proposed GPSM2 as a potential progsnotic marker and therapeutic target, and GPSM3 as a possible target for immunotherapy for breast cancer." (PMID 34572330, 2021). "As the Kaplan–Meier curve showed that higher GPSM2 expression and poor DMFS were consistently and significantly correlated, we next investigated whether GPSM2, along with variables such as age, gender, and tumor stage, were risk factors for survival in breast cancer patients." (PMID 34572330, 2021). "Another important finding of our study was that subcellular localization of GPSM2 was correlated with the expression of DYNC1I1, which indicated a poor prognosis in breast cancer." (PMID 32195179, 2020). "Examination of both GPSM2 and DYNC1I1 is necessary to establish a prognosis in breast cancer patients." (PMID 32195179, 2020). "In summary, examination of both GPSM2 and DYNC1I1 is necessary for accurate prognosis in breast cancer patients." (PMID 32195179, 2020). "PBK/TOPK targets Thr450 of LGN/GPSM2 during mitosis, suggesting that the PBK/TOPK-LGN/GPSM2 pathway could be a potential target for breast cancer therapies." (PMID 41362722, 2026). "However, the clinical value of DYNC1I1 and the relationship between GPSM2 and DYNC1I1 in breast cancer is unclear." (PMID 32195179, 2020). "We believe that assessment of the combination of GPSM2 and DYNC1I1 expression could be a promising biomarker and drug target for breast cancer." (PMID 32195179, 2020). "Correlations between GPSM2 and DYNC1I1 expression levels in patients with breast cancer." (PMID 32195179, 2020). "In our study, we demonstrated by immunoprecipitation that GPSM2 and DYNC1I1 could form a complex in breast cancer cells." (PMID 32195179, 2020). "GPSM2 and DYNC1I1 are known to form a complex in breast cancer cells." (PMID 32195179, 2020). "However, the clinical and prognosis value of GPSM2 in breast cancer has not been elucidated." (PMID 32195179, 2020). "In particular, higher expression levels of GPSM2 indicated worse DMFS time overall and in the following subtypes of breast cancer: ER or PR positive, HER2 positive or negative, luminal A or B, and with or without chemotherapy." (PMID 34572330, 2021).
Chudley-McCullough syndrome (7 papers, 2014 to 2022). "GPSM2 mutations are known to cause brain malformations and hearing loss in Chudley-McCullough syndrome." (PMID 32195179, 2020). "Mutations in GPSM2 cause Chudley-McCullough syndrome (CMCS), an autosomal recessive neurological disorder characterized by early-onset sensorineural deafness and brain anomalies." (PMID 28387217, 2017). "In humans, mutations in the GoLoco protein GPSM2 (also known as LGN) cause brain malformations and hearing loss in the Chudley-McCullough syndrome." (PMID 24466196, 2014).
deafness (5 papers, 2014 to 2024). An inherited or acquired condition characterized by the complete loss of the ability to hear from one or both ears. "Here, we show that mutation of the mouse orthologue of GPSM2 affects actin-rich stereocilia elongation in auditory and vestibular hair cells, causing deafness and balance defects." (PMID 28387217, 2017). "Mutations in GPSM2 cause a rare disease characterized by deafness and brain abnormalities." (PMID 28387217, 2017). "In this study, we show that Gpsm2 and Gαi3 define an ∼200 nm domain at the tip of stereocilia, and that conditional deletion of either gene prevents stereocilia elongation, the likely cause of the early deafness and hearing deficits observed in mutant mice." (PMID 28387217, 2017). "The other 6 variants were associated with recessive forms of deafness (TMPRSS3, GPSM2, BDP1, EPS8, EPS8L2, and PCDH15)." (PMID 33809266, 2021). "On the other hand, in the inner ear the deficits are very similar regardless of the mutation, with early-onset deafness identified in all patients, highlighting the absolute necessity of an intact Gpsm2 protein for hearing." (PMID 28387217, 2017). "Based on our data, the early deafness observed in Gpsm2 cKO would be a consequence of a lack of postnatal elongation of stereocilia in IHC, the auditory sensory cells that are responsible for signal transduction, and which receive the vast majority of afferent innervation." (PMID 28387217, 2017).
hepatocellular carcinoma (5 papers, 2020 to 2024). A malignant tumor that arises from hepatocytes. "A previous study reported that GPSM2 was overexpressed in hepatocellular carcinoma and related to poor prognosis of these patients." (PMID 32195179, 2020). "CHEK1-hsa-mir-195-5p/hsa-mir-497-5p and GPSM2-hsa-mir-122-5p axes were defined as two key pathways in carcinogenesis of hepatocellular carcinoma by combination of in silico analysis and experimental validation." (PMID 32257949, 2020). "All these findings demonstrate that CELSR3, GPSM2, and CHEK1 were upregulated in hepatocellular carcinoma and linked to prognosis of patients with hepatocellular carcinoma." (PMID 32257949, 2020). "For example, in hepatocellular carcinoma and pancreatic cancer, overexpression of GPSM2 promotes tumor progression and is related to prognosis." (PMID 32195179, 2020). "The expression of the GPSM2 gene has also been investigated in liver cancer, which demonstrated a correlation between GPSM2 overexpression and liver cancers associated with hepatitis B virus (HBV) as well as hepatocellular carcinoma cell lines." (PMID 38674408, 2024). "Cancer-related research has revealed that GPSM2 could potentially serve as a drug target and prognostic biomarker in hepatocellular carcinoma, lung adenocarcinoma, and pancreatic cancer." (PMID 34572330, 2021). "All these results together indicate that CHEK1-hsa-mir-195-5p/hsa-mir-497-5p and GPSM2-hsa-mir-122-5p may be key pathways in mediating progression of hepatocellular carcinoma and that link to patients' prognosis." (PMID 32257949, 2020). "Our current findings together with these reports suggest that CHEK1-hsa-mir-195-5p, CHEK1-hsa-mir-497-5p, and GPSM2-hsa-mir-122-5p may be key pathways in pathogenesis of hepatocellular carcinoma." (PMID 32257949, 2020). "CELSR3, GPSM2, and CHEK1 expression were markedly higher in hepatocellular carcinoma than that in normal controls." (PMID 32257949, 2020). "All these findings indicate that high expression of CELSR3, GPSM2, or CHEK1 links to unfavorable prognosis of patients with hepatocellular carcinoma." (PMID 32257949, 2020). "The results suggested that high expression of CELSR3, GPSM2, or CHEK1 indicated poor prognosis in patients with hepatocellular carcinoma." (PMID 32257949, 2020). "Theoretically, miRNAs that potentially bind to oncogenic CELSR3, GPSM2, and CHEK1 should be downregulated in hepatocellular carcinoma and display favorable prognostic roles." (PMID 32257949, 2020). "Next, Oncomine database was further introduced to analyze CELSR3, GPSM2, and CHEK1 expression in hepatocellular carcinoma." (PMID 32257949, 2020). "Therefore, CELSR3, GPSM2 and CHEK1 were considered as three novel potential prognostic biomarkers for hepatocellular carcinoma." (PMID 32257949, 2020). "The rest three genes (CELSR3, GPSM2, and CHEK1) have not been studied for their prognostic values in hepatocellular carcinoma so far." (PMID 32257949, 2020).
pancreatic cancer (5 papers, 2020 to 2024). "Another study in pancreatic cancer showed GPSM2 promoted the proliferation and migration ability of CD133+ pancreatic cancer stem cells." (PMID 32195179, 2020). "A high expression of GPSM2 was also correlated with shorter OS (p = 0.001) and DFS (p = 0.001) in patients with pancreatic cancer." (PMID 38674408, 2024).
hearing loss (4 papers, 2012 to 2022). "In humans, mutations of LGN (also known as GPSM2) cause a syndromic hearing loss suggesting that the directed kinocilium migration and bundle assembly are critical for hearing." (PMID 28266911, 2017). "Our results also uncovered Gαi3 as a specific molecular partner for Gpsm2 during stereocilia elongation, notably within the basal cochlear region, and as a candidate gene for early-onset progressive hereditary hearing loss." (PMID 28387217, 2017). "In this study we show that the Gpsm2/Gαi3 module regulates actin polymerization during stereocilia elongation, and that a pathogenic mutation of either gene leads to abnormally short stereocilia, the likely cause of hearing loss in CMCS patients." (PMID 28387217, 2017).
colon cancer (3 papers, 2023 to 2025). "To elucidate the effect of GPSM2 on colon cancer, we evaluated its effect on the biological behaviour of two colon cancer cell lines." (PMID 40208185, 2025). "Moreover, GPSM2 overexpression was linked to OS (p = 0.02), PPS (p = 0.0002), and relapse-free survival (RFS) (p = 1.8 × 10−6) in colon cancer patients." (PMID 38674408, 2024).
non-small cell lung carcinoma (3 papers, 2020 to 2024). A group of at least three distinct histological types of lung cancer, including non-small cell squamous cell carcinoma, adenocarcinoma, and large cell carcinoma. "For example, in non-small cell lung cancer tissues, GPSM2 was found to be downregulated, and the silencing of GPSM2 enhances the metastatic potential of cancer cells in both in vitro and in vivo environments." (PMID 38674408, 2024).
chronic pancreatitis (2 papers, 2022 to 2024). A chronic inflammatory process causing damage and fibrosis of the pancreatic parenchyma. "This research demonstrated that GPSM2 overexpression in PAAD is associated with a history of chronic pancreatitis, tumor staging, and tumor grade." (PMID 38674408, 2024). "In addition, GPSM2 was associated with chronic pancreatitis, T stage, TNM stage and tumor grade, presumably as an independent prognostic factor." (PMID 36186420, 2022).
glioblastoma multiforme (2 papers, 2020 to 2022). "Among them, the GPSM2 phosphorylation level at the S408 site in glioblastoma multiforme (GLMU) PAADand KIRC and the S565 site in HNSC were significantly increased." (PMID 36186420, 2022).
liver cancer (2 papers, 2020 to 2024). An epithelial or non-epithelial malignant neoplasm that arises from the liver. "Given the gene’s pivotal role in cell growth, cell cycle regulation, migration, and invasion via the phosphatidyl 3-kinase/protein kinase signaling pathway, GPSM2 is proposed as an oncogene and therapeutic target in liver cancer." (PMID 38674408, 2024).
lung adenocarcinoma (2 papers, 2021 to 2024). A carcinoma that arises from the lung and is characterized by the presence of malignant glandular epithelial cells. "Further studies on lung adenocarcinoma have demonstrated that the downregulation of GPSM2 accelerates cell proliferation through the EGFR pathway." (PMID 38674408, 2024).
osteosarcoma (2 papers, 2015 to 2021). A usually aggressive malignant bone-forming mesenchymal neoplasm, predominantly affecting adolescents and young adults. "Across all Ewing and osteosarcoma cell lines eleven genes were found to be either significantly (P < 0.05, Bonferroni correction) repressed (KIF20A, IDH1, SCD, GPSM2, EIF2AK4, HIBCH) or induced (STK19, DNAJC24, MTG2, FAM175B, CYB5D1) following non DNA-damaging XI-006 treatment (0.5 μM)." (PMID 26095524, 2015).
breast invasive carcinoma (1 paper, 2020). "The results demonstrated that GPSM2 could be a prognosis biomarker of invasive breast cancer patients." (PMID 32195179, 2020). "Next, we explored the relationship between nuclear localization of GPSM2 and DYNC1I1 in invasive breast cancer." (PMID 32195179, 2020).